IDH1 (isocitrate dehydrogenase (NADP(+)) 1)
Diseases named in the same sentence as IDH1 in open-access papers (continued):
Sharing a sentence is not in itself a finding about the gene and the disease.
malignant glioma (continued). "The current study was designed to analyze the prognostic implications of IDH1/2 gene alterations and MGMT gene methylation for their individual as well as cumulative impact on outcome of malignant glioma patients with diverse histologies." (PMID 33552543, 2020). "Due to a small number of patients and large heterogeneity of tumor IDH1 status, the authors did not compare blood flow in the wildtype and IDH1-mutant malignant gliomas." (PMID 35741254, 2022). "In the present work, gene expression of the mutant IDH1 effectively enhanced the radiation induced accumulation of γH2AX foci in U-251MG, U-343MG, and LN-229 malignant glioma cells irrespective of the oxygen conditions." (PMID 31242696, 2019).
melanoma (49 papers, 2012 to 2025). A malignant, usually aggressive tumor composed of atypical, neoplastic melanocytes. "By contrast, the frequency of IDH1 mutations was more uniform across melanoma subtypes, ranging from 4% to 9%." (PMID 33024276, 2020). "Particularly, ARID2 and IDH1 genes are involved in chromatin remodelling, which suggests a direct connection between somatic mutations and epigenetic dysfunction in melanoma." (PMID 31861757, 2019). "Mutations in IDH1/2 enzymes have been reported in ~6–10% of melanomas and correlate with the CpG island methylator phenotype (CIMP) cluster-defined DNA methylation profile in melanoma samples in TCGA." (PMID 28396701, 2017). "Whether the acquisition of an NRAS or IDH1 mutation in an atypical DPN may represent a molecular evolution implying a pathway to melanoma progression should be confirmed in a larger series." (PMID 34205480, 2021). "In addition, a subset of melanomas with IDH1 mutations that are significantly associated with co-existing NRAS mutations has been described." (PMID 34205480, 2021). "This study confirmed the co-occurrence of BRAF mutation with IDH1 mutation previously observed, and demonstrated that mutant IDH1 conferred in a BRAF V600E melanoma cell line acquired in vivo growth activities and enhanced activation of the MAPK and STAT3 pathways." (PMID 32850962, 2020). "We found a co-occurrence of IDH1 with NRAS mutations in 3/5 primary melanomas." (PMID 31745173, 2019). "In addition, we have identified that MECOM, a novel, central epigenetic regulatory gene, and TET2/IDH1, critical regulators of DNA demethylation, are frequently mutated in patient melanoma samples." (PMID 26221190, 2015). "Thus, we hypothesized that IDH1 inhibition would synergize with this melanoma associated-chemotherapy." (PMID 36153582, 2022). "IDH1-positive melanoma patients are also potential beneficiaries of this treatment, significantly since inhibition of wild-type IDH1 improved melanoma response to chemotherapy." (PMID 39340537, 2024). "In melanoma patients, mutant IDH1 occurs with a frequency of 3-5%, with the most common hotspot in codon R132." (PMID 39340537, 2024). "Next, we aimed to functionally investigate the roles of NNT and IDH1 in regulating cellular ROS in melanoma." (PMID 39277608, 2024). "Suppression of IDH1 expression in melanoma also decreased NADPH and glutathione levels, resulting in increased reactive oxygen species." (PMID 36153582, 2022). "Along these lines, IDH1 expression similarly affected cell migration of melanoma cells, especially under low glucose conditions." (PMID 36153582, 2022). "Acute glucose withdrawal led to an acute increase in IDH1 mRNA and protein expression in melanoma cells, likely as an adaptive metabolic response, previously observed in pancreatic cancer cells cultured under similar conditions." (PMID 36153582, 2022). "TMZ is known to exhibit oxidative and cytotoxic effects on melanoma and IDH1 inhibition enhances both total cellular ROS and oxidative damage within the nucleus." (PMID 36153582, 2022). "Synergy experiments revealed that pharmacologic IDH1 inhibition rendered TMZ substantially more potent (up to 18-fold at some dosing levels) in melanoma cell lines, A375 and SK-MEL-28." (PMID 36153582, 2022). "Increased IDH1 expression was also observed at mRNA and protein levels in multiple human melanoma cell lines, as compared to normal melanocytes." (PMID 36153582, 2022). "At the functional level, the authors of this study demonstrated in two different animal models that restoring the function of IDH1 or TET2 not only restored the level of 5-hmC in melanoma, but also reduced tumor growth." (PMID 34198758, 2021).
melanoma (continued). "Currently, an ongoing phase 1 trial is underway to evaluate the safety and efficacy of a novel IDH1 inhibitor (LY3410738) in advanced solid tumors with IDH1 mutations, including melanomas (NCT04521686)." (PMID 34831002, 2021). "Similar to IDH1, EZH2, a member of polycomb repressive complex 2, is another recurrent site of gain-of-function mutations in melanoma, although at a lower frequency." (PMID 33024276, 2020). "Of note, it was recently demonstrated that CIMP is prevalent in melanoma patients with specific genetic alterations, including NRAS, ARID2, and IDH1 mutations." (PMID 31861757, 2019). "More rarely, IDH1 and IDH2 mutations have been reported in prostate cancer, B-acute lymphoblastic leukemia, colorectal cancer and melanoma." (PMID 22885298, 2012). "However, our recent knowledge on the genetics of cutaneous melanoma is far more complex and identified actionable gene defects such as NRAS, KIT or IDH1 mutations and NRAS mutant melanoma are now in clinical trials." (PMID 40361349, 2025). "Gained therapies included tyrosine kinase inhibitors (TKIs) in the context of EGFR-mutated NSCLC, trastuzumab deruxtecan for ERBB2-mutated NSCLC, ivosidenib for IDH1-mutated CCA, MEK and RAF inhibitor combination therapies for BRAF V600E melanomas, and PARP inhibitors for BRCA2-mutated HGSOC." (PMID 40399445, 2025). "IDH1 inhibition profoundly impairs the growth of melanoma cells in culture and xenografts in mice." (PMID 36153582, 2022). "Under low glucose conditions, IDH1-deficient cells failed to proliferate, yet IDH1-deficient melanoma cell growth was unaffected under high glucose conditions." (PMID 36153582, 2022). "In this study, IDH1 inhibition with AG-120 potently induced oxidative stress in melanoma cells under nutrient limitation, and effectively synergized with conventional anti-melanoma chemotherapy in cell culture and in mouse melanoma models." (PMID 36153582, 2022). "Ten percent of melanomas (4/39) harbor IDH1 or IDH2 mutations, while no TET mutation has been reported in these tumors." (PMID 34198758, 2021). "To date, no FDA-approved drugs or clinical trials are available for melanoma patients carrying IDH1/IDH2 mutations." (PMID 32850962, 2020). "Mutant IDH1 can reportedly influence the activity of MAPK signaling in melanoma cells." (PMID 29661250, 2018). "IDH1 (isocitrate dehydrogenase 1) mutations are not frequent in melanomas (<10%) but may be of therapeutic relevance in later stages." (PMID 40361349, 2025). "As for triple-wild melanoma, analysis with larger gene panels is worthwhile, as it has a higher probability to find targets for tumor-agnostic targeted therapies in this tumor type, such as RET, NTRK (neurotrophic tyrosine receptor kinase), ALK (anaplastic lymphoma kinase) or even IDH1 mutations." (PMID 40361349, 2025). "In addition, alterations in epigenetic regulators like EZH2, ARID2, and IDH1/2, as well as genomic instability caused by mutations in the DNA damage response (DDR) genes, can lead to the altered transcription of key gene regulators in melanomas." (PMID 34831002, 2021). "Furthermore, mutations in IDH1 or IDH2 genes have not been identified in melanomas, but still, virtually all malignant melanoma samples exhibited either a partial or complete loss of 5-hmC." (PMID 29290954, 2017).
melanoma (continued). "In order to demonstrate a direct transcriptional role of MITF on IDH1 and NNT, chromatin immunoprecipitation (ChIP) with anti-MITF antibodies in UACC257 melanoma cells was performed." (PMID 39277608, 2024). "Restoring 5hmC levels by overexpressing TET2 in melanoma cells, TET1 in breast cancer cells, and IDH1 in renal cancer cells demonstrated inhibitory effects in vitro and in vivo." (PMID 30005692, 2018). "IDH1 was subsequently deleted from melanoma cell lines using CRISPR/Cas9 editing (IDH1-KO)." (PMID 36153582, 2022). "IDH1 mutants can play a dominant negative role in wild-type IDH1 functions, resulting in the increased phosphorylation of MAPK and signal transducer and activator of transcription 3 in melanoma cells." (PMID 29661250, 2018). "Absence of IDH1 and IDH2 mutations in the melanoma (or low occurrence in GBMs) indicates that these mutations are unlikely to be the major determinants promoting a loss of 5-hmC in melanomas, primary GBMs and prostate cancers." (PMID 29290954, 2017). "The analysis of protein and RNA expression levels from the Human Protein Atlas showed that IDH2, which was an essential gene in the melanoma models, but not IDH1 protein, was detected in normal skin cell types and melanoma." (PMID 28806730, 2017). "In support of this in silico result, IDH2 but not IDH1 expression could be measured on the protein level in normal skin cells and melanoma." (PMID 28806730, 2017). "To examine how this increase in ROS affects the survival of melanoma cells, we measured the viability of UACC257 melanoma cells upon MITF, NNT, or IDH1 knockdown in the presence or absence of the thiol antioxidant N-Acetyl-L-Cysteine (NAC)." (PMID 39277608, 2024).
colorectal cancer (45 papers, 2013 to 2026). A primary or metastatic malignant neoplasm that affects the colon or rectum. "Although the incidence of IDH1/2 mutations in colorectal cancers is <1%, evidence supports IDH1/2 mutations as drivers during the early evolutionary phase of tumorigenesis." (PMID 37064137, 2023). "A mathematical analysis of cancer patient data predicted that imbalanced IDH1/2 expression is associated with the 2-HG-inactivating β-oxygenation pathway in colorectal cancer." (PMID 34680237, 2021). "A mutation in the IDH1 gene was first detected in colorectal cancer cells, after which mutations in the IDH1 and IDH2 genes were found in various tumors of neural origin." (PMID 28187001, 2017). "SIRT2 deacetylates IDH1 at K224, promoting its enzymatic activity and α‐ketoglutarate production and inhibiting the invasion and migration of CRC cells, while high acetylation of IDH1 at K224 is significantly associated with distant metastasis and survival in colorectal cancer patients." (PMID 39778006, 2025). "In both gastric and colorectal cancer, expression of IDH1-R132H was associated with tumor stage." (PMID 27655638, 2016). "The associations of IDH1/2 mutations with older age and the BRAF p.V600E substitution have been described in colorectal cancer." (PMID 41413856, 2025). "We also validated 7 of the genes recently identified as colorectal cancer driver genes, including two known drug targets, IDH1 and ERBB2." (PMID 41413856, 2025). "Human IDH1 mutants were originally identified in colorectal cancer and then at a high frequency in gliomas." (PMID 40943163, 2025). "The IDH1 and IDH2 mutations are also present in 0.9% of colorectal cancer, associated with the BRAF V600E mutation, in 0.5% of non-small cell lung carcinoma (NSCLC), co-existing with KRAS mutations and in melanoma, occurring with NRAS mutations." (PMID 39123479, 2024). "Evidence has been provided that IDH1/2 mutants are more frequent in colorectal cancers showing CpG island methylator phenotype, often concurrent with KRAS/BRAF mutations, although with a lower allelic frequency." (PMID 37064137, 2023). "SIRT2 regulates cellular metabolism and metastasis in colorectal cancer through deacetylation of isocitrate dehydrogenase 1 (IDH1), which plays an important role in glutamine metabolism." (PMID 35897717, 2022). "Metabolic assays revealed that exosomes derived from 5FU-resistant cells promoted a decrease in the level of IDH1-mediated NADPH, which is associated with the development of 5FU resistance in colorectal cancer cells." (PMID 34234856, 2021). "Together, these results indicate that drug-resistant colorectal cancer cells secrete exosomes that confer 5FU resistance to sensitive cells by delivering IDH1." (PMID 34234856, 2021). "Recently, K224 in IDH1 was shown to be deacetylated by SIRT2 to inhibit colorectal cancer and liver metastases." (PMID 34065652, 2021). "The absolute protein quantification of iBAQ using LC-MS/MS results showed that IDH1 was highly expressed in the exosomes of 5FU-resistant colorectal cancer cells." (PMID 34234856, 2021). "Both colorectal carcinoma and astrocyte cell lines expressing IDH1/2mt exhibited a hypersensitivity to ionizing radiation or H2O2 compared with those with IDH1/2wt." (PMID 33842477, 2021). "The IDH1 inhibitor IDH305 has also shown significant 2HG reduction in IDH1-mutant colorectal cancer cell lines and substantial brain penetrance in murine models." (PMID 33182517, 2020). "Increased expression of PYCR1 has since been confirmed in different cancers, including melanoma, NSCLC, renal cell carcinoma, breast cancer, colorectal cancer, prostate cancer, hepatocellular carcinoma, and isocitrate dehydrogenase 1 (IDH1)-mutant gliomas." (PMID 33083024, 2020).
colorectal cancer (continued). "AGI-5198, a selective inhibitor of mutant IDH1 (R132H), has been shown to suppress tumor growth and induce differentiation in IDH1-mutant cancer cells, including colorectal cancer models, suggesting its promise in targeted therapy for specific molecular subtypes." (PMID 40697926, 2025). "A IDH1 G97D mutant was found in astrocytomas and colorectal cancer cell lines." (PMID 40943163, 2025). "However, the clinical efficacy of IDH1 inhibitors in colorectal cancer remains unproven and warrants further investigation." (PMID 41413856, 2025). "Indeed, co-administration of pharmaceutical mutant IDH inhibitors and ascorbic acid has been shown to restore TET activity in IDH1-R132H colorectal cancer cell lines." (PMID 39596840, 2024). "Among existing studies, IDH1 is likely a confirmed target of lycorine in colorectal cancer." (PMID 39245716, 2024). "In addition, the average expression level of IDH1 in colorectal cancer tissues was lower than its average expression level in normal colorectal tissues, but this difference was not statistically significant due to the large individual differences." (PMID 36552870, 2022). "In vitro gene overexpression and knockdown were used to determine whether IDH1 promoted the proliferation of the colorectal cancer cell line HCT8 and resistance to 5-Fluorouracil (5FU)." (PMID 34234856, 2021). "In this study, we found that IDH1 was highly expressed in human colorectal cancer tissues and could be used to indicate a high-grade tumor." (PMID 34234856, 2021). "To elucidate molecular mechanism(s) associated with IDH1/2 mutations, we established mouse embryonic fibroblasts (MEF) cells and human colorectal cancer cells stably expressing cancer-associated IDH1R132C or IDH2R172S, and analyzed the change in metabolic characteristics of the these cells." (PMID 34516556, 2021). "This demonstrated D-2HG levels to be elevated in human colorectal cancer tissues compared to non-cancerous tissues, in the absence of mutations of IDH1 or IDH2." (PMID 27824159, 2016). "However, the mechanisms by which IDH1 is involved in colorectal cancer cell proliferation and drug resistance induction remain unclear." (PMID 34234856, 2021). "Therefore, exosomal IDH1 may be the transmitter and driver of chemoresistance in colorectal cancer and a potential chemotherapy target." (PMID 34234856, 2021). "Our previous studies showed IDH1 K224 acetylation, regulated by SIRT2, affected cell metastasis in colorectal cancer." (PMID 34022816, 2021). "For this, we utilized the HCT116 colorectal carcinoma cell line with and without a CRISPR-engineered knock-in IDH1 R132H mutation (HCT116 IDH1 +/R132H)." (PMID 41357766, 2025). "In addition, IDH1 stimulation by deacetylation induces the proteasomal degradation of HIF-1α, which exerts a suppressive effect in colorectal cancer metastasis." (PMID 35897717, 2022). "Previous studies have confirmed that IDH1 mediates chemoresistance in ovarian cancer and endometrial cancer 35, 36, while there is a lack of research on chemoresistance in colorectal cancer." (PMID 34234856, 2021). "Therefore, alterations in IDH1 and IDH2 expression might play different roles during the development of colorectal cancer." (PMID 26376762, 2015). "Therefore, we used the correlation of the expression level of genes with the prognosis of colorectal cancer patients as an evaluation index, and finally identified eight critical enzymes of amino acid metabolism in colon TAMs, namely, ACADM, ACADS, GPX4, GSR, HADH, HMGCL, HMGCS1 and IDH1." (PMID 36552870, 2022). "On the other hand, mutant IDH1 and IDH2 did not exhibit significant increase of intracellular lactate level in HCT116 cells, indicating that augmented Glut1 expression induced by IDH1/2 mutants may not be sufficient to affect glycolytic pathway in colorectal cancer cells." (PMID 34516556, 2021).